PCGEM1 (PCGEM1 prostate-specific transcript)
Diseases named in the same sentence as PCGEM1 in open-access papers (continued):
Sharing a sentence is not in itself a finding about the gene and the disease.
prostate cancer (continued). "Similarly, in prostate cancer, an androgen-induced prostate-specific LncRNA named prostate cancer gene expression marker 1 (PCGEM1) was discovered to increase glucose uptake and glycolysis for adequate energy supply and the proliferation and survival of LNCaP cells." (PMID 36674820, 2023). "Prostate cancer-associated long-noncoding RNA 1 (PRNCR1) and PCa gene expression marker 1 (PCGEM1) are highly expressed in CRPC and known to be involved in the AR signaling pathway; however, knockdown of either PRNCR1 or PCGEM1 inhibited the growth of CRPC cells in vivo." (PMID 36902032, 2023). "LncRNA PCGEM1 (prostate cancer gene expression marker 1) is an androgen-induced prostate-specific lncRNA, which has been confirmed to regulate the metabolism including the tricarboxylic acid cycle, glutamine metabolism and pentose phosphate pathway of prostate cancer by activating c-Myc." (PMID 33849550, 2021). "Here, we sought to evaluate whether PCGEM1 and PRNCR1 are associated with prostate cancer." (PMID 24727738, 2014). "Similarly, PCGEM1, PCA3 or PRNCR1 are three lncRNAs exclusively associated with prostate cancer." (PMID 23887658, 2013). "In contrast, another two prostate-specific lncRNAs (PCGEM1 and PCA3) are overexpressed in prostate cancer and promote the cell proliferation ability and inhibit the cell apoptosis ability of prostate cancer cells." (PMID 36289466, 2022). "For example, PCA3, PCGEM1, and PRNCR1 are highly expressed in prostate cancer, while differential HULU expression is related to liver cancer and liver metastasis." (PMID 36389111, 2022). "In prostate cancer, AR activated the expression of several lncRNAs, such as ARLNC1, PCGEM1, and SOCS2-AS1, via binding to the androgen response element (ARE) sites in the lncRNA locus and promoting tumor progression." (PMID 32661324, 2020). "Other lncRNAs, such as PCGEM1, HOTAIR, and AK001796, were overexpressed in most cases of prostate cancer and phytochemical-induced anticancer activities." (PMID 31208095, 2019). "Together, these results demonstrate a novel mechanism of p54/nrb-mediated expression of PCGEM1 and AR3, contributing to castration resistance in prostate cancer." (PMID 27682980, 2016). "Of the long noncoding RNAs involved in prostate carcinogenesis, PCGEM1 and PRNCR1 (prostate cancer noncoding RNA1) have been identified as playing critical roles via coordination with AR." (PMID 26110379, 2015). "The prostate cancer gene expression marker 1 (PCGEM1) does not code for a protein, but it is a long noncoding RNA PCGEM1 (lncRNA PCGEM1)." (PMID 36038612, 2022). "The first reported prostate tissue-specific and prostate cancer-associated, long non-coding (lnc) RNAs were differential display 3 (DD3)/(PCA3) and a prostate cancer gene expression marker 1 (PCGEM1); however, PCA3 was found to be over-expressed in virtually all prostate cancers." (PMID 31013716, 2019). "A more recent study by Prensner and colleagues, however, refutes that PCGEM1 and PRNCR1 interact with the androgen receptor and that either gene is a component of androgen receptor signaling or is involved in castration-resistant prostate cancer." (PMID 25849966, 2015). "Recently, two lncRNAs, PCGEM1 and PRNCR1, have been suggested in prostate cancer to act as mediators of castration-resistance disease by binding, in a direct and sequential fashion, to the androgen receptor (AR), causing ligand-independent activation of its gene expression programs." (PMID 24727738, 2014). "First, we asked whether PCGEM1 and PRNCR1 are highly overexpressed in aggressive prostate cancer, as suggested by others." (PMID 24727738, 2014). "PCGEM1 is another example of a ncRNA found over-expressed in prostate cancer but it differs from PCA3 in that it does not locate in an intronic region of another gene." (PMID 19319183, 2009).
prostate cancer (continued). "PCGEM1 was chosen in addition to PCA3 as it has previously been demonstrated to be a prostate tissue-specific, androgen-regulated non-coding RNA that is functionally involved in the development of prostate cancer and significantly over-expressed in AA men with prostate cancer." (PMID 36768533, 2023). "Moreover, the reciprocal negative control relationship between PCGEM1 and miR-145 regulates both prostate cancer cells proliferation and tumor growth." (PMID 26448935, 2015). "PCGEM1 is upregulated in clinically localized cancer, confirming the known literature; however PRNCR1 expression does not demonstrate a convincing association with prostate cancer." (PMID 24727738, 2014). "However, the specific mechanism of PCGEM1 within prostate cancer (PCa) has not been elucidated." (PMID 35109849, 2022). "Besides, the lately study elaborated that PCGEM1 and PRNCR1, bound successively to the androgen receptor and strongly enhanced both ligand-dependent and ligand-independent androgen-receptor-mediated gene activation programs and proliferation in prostate cancer cells." (PMID 28915709, 2017). "Thus, we conclusively demonstrate that PCGEM1 and PRNCR1 are not prognostic lncRNAs in prostate cancer and we refute suggestions that these lncRNAs interact in AR signaling." (PMID 24727738, 2014).
gastric cancer (10 papers, 2019 to 2025). A primary or metastatic malignant neoplasm involving the stomach. "Evidence from another study suggested that PCGEM1 also improves the invasive ability of gastric cancer cells by increasing the level of prolyl 4-hydroxylase subunit alpha 2 (P4HA2)." (PMID 35055115, 2022). "Hypoxia-inducible factor-1α not only is an independent prognostic factor of gastric cancer but also, under hypoxic conditions, can stimulate the overexpression of prostate cancer gene expression marker 1 (PCGEM1)." (PMID 36187789, 2022). "The regulation axis of PCGEM1/miR-129-5p has been reported in gastric cancer and cervical cancer in previous studies." (PMID 36193492, 2022). "PCGEM1 promotes gastric cancer metastasis and invasion by regulating SNAI1." (PMID 35109849, 2022). "Recent findings reveal that PCGEM1 may also function in other cancers, such as gastric cancer and endometrial carcinoma." (PMID 33589577, 2021). "In gastric cancer cells, PCGEM1 could promote the invasion and metastasis through activating the expression of SNAI1, a key transcription factor of EMT, though the underlying mechanism remains elusive." (PMID 32370770, 2020). "For instance, lncRNA PCGEM1 was found to be overexpressed in gastric cancer, and could be induced by hypoxia." (PMID 32370770, 2020). "However, some researches showed that PCGEM1 has abnormal expression level in a variety of malignant tumors, which can affect the progress of cancer cells, including cervical carcinoma, renal carcinoma, gastric cancer, and endometrial carcinoma." (PMID 36193492, 2022). "PCGEM1 stabilizes SNAI1 proteins via physically interacting with them, serving as a pro-migratory and -invasive lncRNA in gastric cancer." (PMID 35055115, 2022). "Moreover, PCGEM1 is capable to induce epithelial–mesenchymal transition (EMT) and metastasis via increasing SNAI1 expression in gastric cancer cells." (PMID 31832017, 2019).
ovarian carcinoma (8 papers, 2018 to 2024). A malignant neoplasm originating from the surface ovarian epithelium. "PCGEM1 overexpression might cause carcinogenesis in ovarian cancer and affect its development by modulating YAP, P70S6K, RhoA, Bcl-xL and MMP2 protein levels." (PMID 35109849, 2022). "In ovarian cancer, another legal gynecological malignancy, PCEGM1 was also observed to be highly expressed in ovarian cancer tissues and PCGEM1 was higher in poor differentiation group than in well differentiation group." (PMID 35265529, 2022). "Results of the study showed that the expression level of PCGEM1 was significantly higher in ovarian cancer tissues than in normal ovarian tissues (14 normal ovarian tissue and 50 epithelial ovarian cancer tissue specimens; p < 0.05)." (PMID 34771549, 2021). "Alternatively, the ability of miR-129-5p in the inhibition of ovarian cancer cell proliferation and survival was defined previously, which highlighted the role of the PCGEM1 and miR-129-5p as the treatment options in epithelial ovarian cancer." (PMID 34771549, 2021). "PCGEM1 enhances ovarian cancer cell proliferation, migration, and invasion, but decreased cell apoptosis through upregulating RhoA, YAP, MMP2, Bcl-xL, and P70S6K expression." (PMID 31832017, 2019). "Moreover, overexpressed PCGEM1 can expedite cell proliferation in ovarian carcinoma via RhoA pathway." (PMID 32787827, 2020). "Overexpression of the lncRNA PCGEM1 (prostate cancer gene expression marker 1) promotes cancer growth by upregulating protein expression of RhoA and its downstream factors YAP (Yes-associated protein), MMP2 (matrix metalloproteinase 2), Bcl-xL and P70S6K in ovarian cancer." (PMID 31248165, 2019). "Besides, PCGEM1 expression level is overexpressed in epithelial ovarian cancer tissues." (PMID 31832017, 2019). "However, lncRNA prostate cancer gene expression marker 1 (PCGEM1), whose high expression not only aggravates ovarian cancer but also can induce tumorigenesis and endometrial cancer progression, has not been studied in CC." (PMID 38948025, 2024).
cervical cancer (7 papers, 2019 to 2025). A primary or metastatic malignant neoplasm involving the cervix. "PCGEM1 accelerates cell proliferation, invasion and migration by targeting miR-182, while overexpression of PCGEM1 is associated with dismal prognostic outcome, lymph node metastasis and distant metastasis in cervical cancer cases." (PMID 35109849, 2022). "PCGEM1 upregulation stimulated proliferation, invasion, migration, and cell cycle process and reduced apoptosis in cervical cancer cells." (PMID 35928868, 2022). "For example, previous research results indicated that lncRNA PCGEM1 can regulate the expression of miR-642a-5p in cervical carcinoma, the expression of miR-433-3p in renal carcinoma, the expression of miR-590-3p in non-small-cell lung cancer, and so on." (PMID 36193492, 2022). "Altogether, PCGEM1 exerted cervical cancer progression via modulation of miR-182 and FBXW11." (PMID 35928868, 2022). "LncRNA PCGEM1 expression was remarkably increased in cervical cancer specimens, which was associated with FIGO stage, lymph node metastasis, poor survival and distant metastasis in cervical cancer patients." (PMID 35928868, 2022).
prostate tumors (6 papers, 2016 to 2023). "The prostate cancer gene expression marker 1 (PCGEM1) was initially identified as an androgen-induced prostate-specific lncRNA whose overexpression is highly associated with prostate tumors." (PMID 28704924, 2017). "A prostate-specific gene, PCGEM1, was identified as long non-coding RNA, preferentially expressed in prostate tumors, and PCGEM1 expression was significantly higher in the PCa of African American men than in Caucasian American men." (PMID 38201592, 2023). "On one hand, it kills prostate tumor cells; on the other hand, it also induces PCGEM1 such that these surviving cells become castration resistant." (PMID 27682980, 2016). "Prostate cancer gene expression marker 1 (PCGEM1), a lncRNA highly associated with prostate tumors, significantly induces genes involved in multiple metabolic pathways such as aerobic glycolysis, pentose phosphate shunt and NADPH generation used for redox homeostasis." (PMID 33652661, 2021). "It has been recently shown that DIM can suppresses prostate tumor growth possibly by downregulation of AR24, however, little is known with regard to its role in PCGEM1 expression." (PMID 27682980, 2016). "Another lncRNA involved in glutamine metabolism is PCGEM1 an androgen-induced prostate specific lncRNA, which regulates expression of enzymes such as GLS, Glutathione Reductase (GSR), and type I gamma-glutamyltransferase (GGT1) in prostate tumors." (PMID 27551267, 2016).
renal carcinoma (6 papers, 2018 to 2022). A carcinoma arising from the epithelium of the renal parenchyma or the renal pelvis. "In the past two decades, many studies have suggested crucial functions of PCGEM1 in the initiation and progression of various cancers, such as renal carcinoma and endometrial cancer (EC)." (PMID 35265529, 2022). "According to a previous study, PCGEM1 can interact with miR-433-3p to modulate renal carcinoma progression." (PMID 32787827, 2020). "For example, PCGEM1/miR-433-3p/FGF2 signaling pathway contributes to malignant phenotypes of renal carcinoma cells." (PMID 33088221, 2020). "Additionally, PCGEM1 overexpression is positively correlated with tumor differentiation, TNM stage and lymph node metastasis in both renal carcinoma and oral carcinoma." (PMID 35265529, 2022).
endometrial carcinoma (4 papers, 2020 to 2024). A malignant tumor arising from the epithelium that lines the cavity of the uterine body. "Previous study has shown that PCGEM1 over-expression induced tumorigenesis and endometrial carcinoma progression by regulating miR-129-5p/STAT3 signaling." (PMID 38948025, 2024). "PCGEM1 also enhances endometrial carcinoma cell proliferation and apoptosis by targeting STAT3 via downregulation of miR-129." (PMID 36915057, 2023). "The lncRNA PCGEM1 is a relatively novel lncRNA, and a previous study demonstrated that PCGEM1 is capable of enhancing endometrial carcinoma cell proliferation and apoptosis by targeting STAT3 via sponging of miR-129." (PMID 36915057, 2023). "It has also been proven that PCGEM1 can affect the cellular processes in endometrial carcinoma via sponging miR-129-5p and regulating STAT3." (PMID 32787827, 2020). "Given the importance of PCGEM1 in promoting endometrial carcinoma cell proliferation, we sought to determine whether PCGEM1 plays an important role in endometriosis." (PMID 36915057, 2023). "Furthermore, PCGEM1 expression levels have been found to be higher in endometrial carcinoma tissues." (PMID 36915057, 2023). "However, despite promising results indicating its oncogenic activity in endometrial carcinoma tissues, whether PCGEM1 exhibits similar activity in endometriosis remains unknown." (PMID 36915057, 2023).
lung cancer (4 papers, 2016 to 2022). A malignant neoplasm involving the lung. "LncRNA PCGEM1 found in ADC only as activated upstream regulator, plays an important oncogenic role in cancer progression and is widely implicated in a variety of human cancers, including lung cancer." (PMID 35512017, 2022).
colorectal cancer (3 papers, 2019 to 2022). A primary or metastatic malignant neoplasm that affects the colon or rectum. "Cellular functional studies showed that lncRNA PCGEM1 silencing inhibited the proliferation, invasion, and migration of colorectal cancer." (PMID 36193492, 2022). "In conclusion, PCGEM1 mediates the proliferation, invasion, and migration of colorectal cancer cells by targeting miR-129-5p/SOX4 axis." (PMID 36193492, 2022). "PCGEM1 mediates the proliferation, invasion, and migration of colorectal cancer cells by targeting miR-129-5p and regulates the expression of SOX4." (PMID 36193492, 2022). "The results of rescue experiments confirmed that SOX4 served as the functional protein of PCGEM1/miR-129-5p in colorectal cancer." (PMID 36193492, 2022). "Similar results were also found in experiments of tissue level, which indicated that the PCGEM1 expression in colorectal cancer tissues was 2.35 times higher than that in adjacent normal tissue." (PMID 36193492, 2022). "We found that PCGEM1 is overexpressed in colorectal cancer cells and tissues, while miR-129-5p is underexpressed." (PMID 36193492, 2022). "Functionally, PCGEM1 silencing can significantly inhibit the proliferation, invasion, and migration of colorectal cancer cells." (PMID 36193492, 2022). "The results above showed that PCGEM1 can act as an oncogene in colorectal cancer and targets the expression of miR-129-5p." (PMID 36193492, 2022). "In this study, dysregulated lncRNA PCGEM1 was found in colorectal cancer tissues/cells and identified to be significantly upregulated." (PMID 36193492, 2022). "Mechanically, PCGEM1 acted as a sponge for miR-129-5p and absorbed its expression, and miR-129-5p was found to target SOX4, constructing the axis of PCGEM1/miR-129-5p/SOX4 in colorectal cancer." (PMID 36193492, 2022). "In addition, this study only conducted in vitro cell experiments and clinical tissue detection; in vivo experiments in animal models are needed to further clarify the role of lncRNA PCGEM1/miR-129-5p/SOX4 regulatory axis in colorectal cancer." (PMID 36193492, 2022). "This study is aimed at identifying the role of PCGEM1 in colorectal cancer." (PMID 36193492, 2022). "In addition, the Pearson correlation analysis found a significant correlation between PCGEM1 and miR-129-5p expression levels in colorectal cancer tissue (Pearson r = −0.3788, P = 0.0248)." (PMID 36193492, 2022). "Furthermore, rescue experiments indicated that lncRNA PCGEM1 can regulate colorectal cancer proliferation, invasion, and migration through targeting miR-129-5p/SOX4." (PMID 36193492, 2022). "However, the relationship between PCGEM1 and colorectal cancer is still unclear yet." (PMID 36193492, 2022). "In addition, overexpressing and silencing PCGEM1 in colorectal cancer cells could make the expression level of miR-129-5p downregulated and upregulated, respectively, suggesting that PCGEM1 can negatively target miR-129-5p." (PMID 36193492, 2022). "However, the effect and mechanism of PCGEM1 in colorectal cancer is still unknown." (PMID 36193492, 2022). "This study finds that lncRNA PCGEM1 and SOX4 are overexpressed in colorectal cancer, while miR-129-5p is underexpressed." (PMID 36193492, 2022). "In experiments of cell level, we found that when compared with NCM60, the four colorectal cancer cell lines (HT29, LoVo, HCT116, and SW480) had significant increased expression level of PCGEM1, with the multiples of 2.28, 2.20, 2.51, and 2.28." (PMID 36193492, 2022). "At first, the sample size of clinical patients is not large enough, and more follow-up data need to be collected to further evaluate the relationship between the expression levels of lncRNA PCGEM1, miR-129-5p, and SOX4 in colorectal cancer tissues and patient prognosis." (PMID 36193492, 2022). "The effect of PCGEM1 in CRC has not been well studied yet; we hypothesize that PCGEM1 could participate in regulating the development of colorectal cancer." (PMID 36193492, 2022).
non-small cell lung carcinoma (3 papers, 2014 to 2022). A group of at least three distinct histological types of lung cancer, including non-small cell squamous cell carcinoma, adenocarcinoma, and large cell carcinoma. "LncRNA levels are strongly associated with aberrant gene expression that may drive cancer development and progression, such as HOTAIR in non-small cell lung cancer (NSCLC), PRNCR1 (also known as PCAT8) and PCGEM1 in prostate cancer, and MEG3 in cervical cancer and meningiomas." (PMID 25496320, 2014).
osteoarthritis (3 papers, 2020 to 2023). A noninflammatory degenerative joint disease occurring chiefly in older persons, characterized by degeneration of the articular cartilage, hypertrophy of bone at the margins and changes in the synovial membrane. "Aprostate-specific lncRNA prostate cancer gene expression marker 1 (PCGEM1) is apowerful indicator that distinguishes early osteoarthritis from late-stageosteoarthritis." (PMID 32520202, 2020). "As for osteoarthritis, it was reported the synovial fluid samples from late-stage patients had a significantly higher expression of exosomal lncRNA PCGEM1 compared to early-stage patients, who in turn had a significantly higher expression of exosomal lncRNA PCGEM1 compared to the control group." (PMID 32937850, 2020).